MMP12 (matrix metallopeptidase 12)
Diseases named in the same sentence as MMP12 in open-access papers (continued):
Sharing a sentence is not in itself a finding about the gene and the disease.
cervical carcinoma (continued). "MMP12 knockdown did not influence the viability of cervical cancer cells but clearly inhibited cell migration and invasion both in vitro and in vivo." (PMID 33958583, 2021). "Upregulation of MMP-12 protein by the overexpression of Nup88 was also observed in one other cervical cancer cell line and two prostate cancer cell lines but not 293 cells." (PMID 34331103, 2021). "Moreover, we demonstrated that MTA2 knockdown can downregulate MMP12 expression and the metastatic potential of HPV-positive cervical cancer cells." (PMID 33958583, 2021). "Here, we observed that ASK1 activation is crucial to the downregulation of MMP12 through the MEK3/p38 cascade in response to MTA2 knockdown, suggesting that the inhibited ASK1/MEK3/p38 axis may play an important role in the progression of cervical cancer." (PMID 33958583, 2021). "SCs displayed increased expression of MMP-2, MMP-9, and MMP-12 at the protein level after co-cultivation with cervical cancer cells, whereas no change in the expression of these MMPs was detected in HeLa and ME-180 cells, differing from previous report about pancreatic adenocarcinoma cells." (PMID 32064233, 2020). "Interestingly, in a previous study no expression of MMP-12 or MMP-16 was found in HPV harboring cervical carcinoma cell lines." (PMID 22863036, 2012).
colitis (12 papers, 2015 to 2025). Inflammation of the colon. "In a study of colitis, MMP-12, served as a key pathogenic factor, can degrade the basement membrane laminin, therefore facilitating macrophage transmigration across the intestinal tight junctions." (PMID 37359523, 2023). "While MMP12 was previously shown to be critical for Mφ transmigration across intestinal epithelial cell layers in severe colitis, we found that MMP12 attenuates Mφ mobility on Matrigel/elastin-coated surfaces resembling structural features of the ECM." (PMID 38069304, 2023). "Further, an important role of MMP-12 in IBD pathogenesis was suggested by a study showing that MMP-12 knockout mice were protected against drug-induced colitis." (PMID 27455234, 2016). "MMP-12 was also shown to be upregulated in IBD patients as well as T-cell mediated model of colitis and contribute to epithelial degradation and MMP-12−/− mice were protected against TNBS induced colitis." (PMID 25948887, 2015). "In fact, Mmp12−/− mice displayed attenuated colitis severity in both acute and chronic DSS-induced colitis, and this was caused by a decrease in the epithelial permeability and, more importantly, by a reduction in the transmigration of macrophages through the intestinal epithelium." (PMID 38542140, 2024). "Most MMPs, such as MMP-2, MMP-3, MMP-7, MMP-9, MMP-10, MMP-12, and MMP-13 are increased in colitis and CAC." (PMID 36776395, 2022). "Recent study showed that MMP12 mediated the degradation of basement membrane laminin and the transmigration across intestinal epithelial tight junctions of macrophages, and increased severity of DSS-induced colitis of mice." (PMID 35493520, 2022).
Arthritis (11 papers, 2005 to 2023). Inflammation of a joint. "With loss-of-MMP12 there was an increased incidence of arthritis as compared to Mmp12+/+ MRL/lpr mice." (PMID 29925830, 2018). "CD163+ macrophages expressed a pro-inflammatory profile of biomarkers (activin A, TNFα, and MMP-12) in synovial tissue from all arthritis subtypes studied, while in paired samples of synovial fluid only activin A levels were widely detected." (PMID 33679701, 2020). "Twenty-eight days after induction of collagen-induced arthritis, male Mmp12–/– B10.RIII mice (n = 20) exhibited more severe arthritis, with increased ankle width and histopathological scores compared with male Mmp12+/+ B10.RIII mice (n = 18)." (PMID 29925830, 2018). "MMP-12 has been shown to dampen inflammation in arthritis by inactivating complement C3 and degrading neutrophil extracellular traps (NETS)." (PMID 29216931, 2017). "As the DA.Ncf1E3 congenic rats carry the arthritis-protecting variant of Ncf1, one might speculate that the effect caused by the functional Ncf1 is to generate a resistance to the effect from induction of Ass, Cxcl9 and Mmp12 genes, which might otherwise contribute to the development of arthritis." (PMID 17490473, 2007). "Notably, this loss-of-controlled evolution in macrophage populations over time was also a feature of Mmp12–/– B10.RIII arthritis at 28 days and lymphadenopathy in MRL/lpr mice at 96 days." (PMID 29925830, 2018). "MMP-12 mRNA level was already increased at day 3 after the onset of arthritis." (PMID 15743487, 2005). "Over-expression of MMP-12 has been shown to enhance the development of inflammatory arthritis in transgenic rabbits, and there is increased expression of MMP-12 in RA synovial tissues compared with osteoarthritis (OA), suggesting that MMP-12 may play a destructive role in arthritis." (PMID 16919164, 2006). "We observed an important role for the MMP12/IFN-γ processing axis in acute inflammation in models of peritonitis and in the acute collagen-induced model of arthritis." (PMID 29925830, 2018). "The role of MMP12 was also apparent in MRL/lpr mouse models of arthritis and lupus, especially after CFA hyperinduction of IFN-γ, where differences in its activity would be more manifest depending upon MMP12 initiated inactivation and clearance." (PMID 29925830, 2018). "MMP-12 was very strongly and significantly overexpressed in the course of AIA after arthritis induction." (PMID 15642138, 2005). "IFN-γ-stimulated arthritis induced a marked increase in MMP-3, MMP-12 and MMP-13 mRNA levels in the cartilage layers of both WT controls and p47phox-/- mice, in comparison with the cartilage of naive knee joints (Δ Ct ranging from 3 to 9)." (PMID 15987491, 2005). "Therefore, the expression of activin A, MMP12 and TNFα designates the GM-CSF-dependent pro-inflammatory state of CD163+ ST macrophages in undifferentiated and established arthritis." (PMID 33679701, 2020).
colorectal cancer (10 papers, 2005 to 2025). A primary or metastatic malignant neoplasm that affects the colon or rectum. "Among them, MMP12 is known to be associated with increased survival in colorectal cancer, which has become an important therapeutic target (Said, Raufman & Xie, 2014)." (PMID 32704448, 2020). "Upregulation of several MMPs including MMP7, MMP10 and MMP12 in cancerous tissue and adverse association with survival has been evaluated likewise in colorectal cancer." (PMID 27431388, 2016). "Moreover, patients with single nucleotide polymorphism (SNP) in the promotor region of MMP12 display a higher risk of suffering from disseminated colorectal cancer and for stromal MMP12 expression in colorectal cancer liver metastases an association with impaired survival is observed." (PMID 27431388, 2016). "Among them, MMP12 was highly expressed in colorectal cancer tissues, while ARMCX2, CEBPA, CXCL13, FABP4, HOXC6, SIGLEC1 and VSIG4 were more expressed in normal tissues than in cancer tissues." (PMID 36544770, 2022). "Overexpression of HME/MMP12 mRNA in patients with colorectal carcinoma exhibited a significantly better survival outcome compared with patients with normal HME/MMP12 mRNA expression." (PMID 33935718, 2021). "Consistently with MMP7 and MMP10 also overexpression of MMP12 in colorectal cancer specimen is reported." (PMID 27431388, 2016). "Yang and colleagues reported that overexpression of MMP12 in tumors correlated with increased survival and decreased tumor neovascularization in colorectal cancer patients." (PMID 15987457, 2005). "There is a correlation between tumor-derived IL-6 and macrophage MMP12 in colorectal cancer." (PMID 34863141, 2021). "In order to reveal the potential association between tumor-derived IL-6 and macrophages, we performed that mouse macrophage RAW264.7 cells were co-cultured with mouse colorectal cancer MC38 cells / CT26 cells, after 72 h to detect MMP12 in macrophages by western blot." (PMID 34863141, 2021). "Thus, we detected the expression of MMP9, MMP12, and TWIST1 in colorectal cancer cells." (PMID 26820130, 2016).
COVID-19 (10 papers, 2021 to 2023). A disease caused by infection with severe acute respiratory syndrome coronavirus 2. "With the help of other molecules, including cytokines, chemokines, and adhesion molecules, MMP-12 is potentially involved in developing neurological symptoms resulting from COVID-19." (PMID 37372128, 2023). "For example, increased serum concentrations of neutrophil elastase (C36-generating enzyme) and MMP-12 (C42-generating enzyme) have been detected in severe COVID-19 patients." (PMID 35264629, 2022). "Our study showed a consistent upregulation of MMPs (MMP1, MMP7, MMP10, and MMP12) in post-COVID-19 individuals, suggesting ongoing remodeling processes in individuals that experienced mild disease." (PMID 36405747, 2022). "Kidney failure can be mediated via IL-15 and MMP12, which are often involved in monocyte response—a critical part of COVID-19 activation." (PMID 34608231, 2021). "In addition, power calculations were carried out to determine the ability of MMPs (MMP8, MMP12, MMP13) to distinguish MIS-C from acute COVID-19 and other tropical diseases." (PMID 36544496, 2022). "A combination of 3 MMPs (MMP-8, MMP-12 and MMP-13) produced an area under the curve (AUC) of 0.89–1, indicating that these MMPs could distinguish MIS-C from acute COVID-19 with 83–92% sensitivity and 80–85% specificity." (PMID 36544496, 2022). "Interestingly, the increased protease:anti-protease ratio seen with COVID-19 may be due to cleavage of AAT by proteases, as evinced by increased AAT fragments C-36 (cleavage product of neutrophil elastase) and C-42 (cleavage product of MMP-12)." (PMID 37294003, 2023).
myocardial infarction (9 papers, 2012 to 2024). Gross necrosis of the myocardium, as a result of interruption of the blood supply to the area, as in coronary thrombosis. "Moreover, MMP12 was identified as a resolution-promoting factor in myocardial infarction, a symptom of chronic Chagas disease, inducing M2 macrophages and the secretion of anti-inflammatory cytokines." (PMID 39000601, 2024). "Similarly, in a mouse model of myocardial infarction, prolonged inflammation in Mmp12 KO mice resulted in a worsened neutrophil influx." (PMID 39456786, 2024). "The Mφ-specific matrix metalloproteinase, i.e., MMP12, is identified as an endogenous resolution promoting factor in the events of myocardial infarction, and it plays a protective role by arresting inflammatory pathways and neutrophil infiltration in various diseases." (PMID 33172999, 2020). "In addition, plaques from patients with a previous coronary intervention or myocardial infarction had a significantly higher percentage of MMP-12–positive macrophages." (PMID 23316311, 2012).
pancreatic cancer (9 papers, 2005 to 2025). "Of these, the expression of several matrix metalloproteinases was decreased, including Mmp10, Mmp12, and Mmp13; these metalloproteinases have been implicated in epithelial-to-mesenchymal transition, invasion, and metastases in pancreatic cancer." (PMID 41373844, 2025). "MMP12 was also revealed to be a potential diagnostic biomarker for pancreatic carcinoma." (PMID 35831362, 2022). "Our findings revealed a novel mechanistic link between macrophage reprogramming and neural invasion, positioning the SRC‐1/STAT1/MMP12 axis as a promising therapeutic target for mitigating PNI in pancreatic cancer." (PMID 40985319, 2025). "Among those, MMP-7 and MMP-12 displayed high sensitivity and specificity in discriminating between serum samples of pancreatic cancer patients and healthy donors." (PMID 25483099, 2014). "ROC analysis of corresponding serum samples reveals MMP-7 and MMP-12 as strong classifiers for the diagnosis of patients with pancreatic cancer vs. healthy control donors." (PMID 25483099, 2014). "Steroid receptor coactivator‐1 (SRC‐1) reprograms tumor‐associated macrophages (TAMs) via signal transducer and activator of transcription 1(STAT1)‐mediated matrix metallopeptidase 12 (MMP12) transcription to drive perineural invasion (PNI) in pancreatic cancer." (PMID 40985319, 2025). "We confirmed that PNI involves interactions between TAMs, tumor cells, and nerve cells, suggesting that interventions targeting TAM phenotypes and MMP12 secretion may represent potential strategies for preventing PNI in patients with pancreatic cancer." (PMID 40985319, 2025). "Therefore, SRC‐1 may influence pancreatic cancer PNI by regulating MMP12 secretion from TAMs." (PMID 40985319, 2025). "Even in a small subgroup of patients with early stage pancreatic cancer (UICC II), MMP-7 and MMP-12 were good classifiers to distinguish between patients with pancreatic cancer and healthy donors." (PMID 25483099, 2014). "In corresponding serum samples, we identified serum-derived MMP-7 and MMP-12 as strong classifiers to diagnose patients and tumor-derived PDGF-BB and MMP-1 as potential prognostic biomarkers in pancreatic cancer." (PMID 25483099, 2014). "Subgroup ROC analysis of stage II – IV pancreatic cancer revealed similar results for MMP-7 and MMP-12." (PMID 25483099, 2014). "As a coactivator of STAT1, SRC‐1 promotes MMP12 transcription, suggesting that SRC‐1 may be an attractive therapeutic target for PNI in pancreatic cancer." (PMID 40985319, 2025). "Exogenous IL-13 was shown to induce the expression of MMPs including MMP-9, MMP-12, and MMP-14, which were related to pancreatic cancer invasion in IL-13Rα2-positive pancreatic cancer cells independent of STAT6 phosphorylation." (PMID 33804263, 2021).
abdominal aortic aneurysm (8 papers, 2013 to 2025). Enlargement and ballooning of the vessel that supplies arterial blood to the abdomen, pelvis and legs. "MMP12, a member of matrix metalloproteinases family, has significant elastolytic activity, and has been linked to large artery stroke as well as aortic abdominal aneurysms, and these outcomes have also been associated with raised B-Cd." (PMID 31114450, 2019).
gastric cancer (8 papers, 2007 to 2025). A primary or metastatic malignant neoplasm involving the stomach. "The dysregulation of MMP12 (also known as human macrophage metalloelastase) has been hypothesized to be linked to all sorts of cancers, such as gastric cancer, but it predicts different prognoses in different tissues." (PMID 36471693, 2022). "We identified 12 driver genes potentially involved in the gastritis-to-cancer transformation, with CHI3L1, MMP12, CXCL6, IDO1, and CCL20 emerging as the top five genes via a early gastric cancer diagnostic model." (PMID 40108688, 2025). "A study related to gastric cancer indicated that MMP12 and COL1A1 collectively promote cancer progression." (PMID 39124881, 2024). "Consistently, the present study also elaborated that gastric cancer patients with MMP12 high expression had longer overall survival." (PMID 36471693, 2022). "Though contradictory reports exist concerning its prognostic value, it was suggested that MMP-12 expression indeed is beneficial and correlates with higher survival rates amongst gastric cancer patients." (PMID 28398251, 2017). "Finally, great of relevance, we found an upregulation of Matrix Metalloproteinase family (MMP1, MMP3, MMP10, MMP12), that are overexpressed in gastric cancer as a result of NF-Kb activation thus promoting migration and invasion, and are associated with poor prognosis." (PMID 34012923, 2021). "Patients with MMP12-positive gastric cancer tend to exhibit worse overall survival compared to MMP12-negative patients." (PMID 37889539, 2023). "MMP-12 is not detectable in H. pylori infected gastric cancer cell lines; however its presence was shown in gastric cancer tissue." (PMID 28398251, 2017).
osteosarcoma (8 papers, 2020 to 2025). A usually aggressive malignant bone-forming mesenchymal neoplasm, predominantly affecting adolescents and young adults. "The same study also found that all-trans retinoic acid (ATRA) inhibited M2 polarization of TAMs via downregulating MMP12 expression, thereby limiting osteosarcoma." (PMID 34691083, 2021). "We found that MMP12 expression is negatively correlated with GNG12 expression, and high MMP12 expression can also predict poor osteosarcoma PFS." (PMID 34691083, 2021). "Specifically, MMP12, a member of the MMP family, is associated with the metastatic phenotype in various cancers, including non-small cell lung cancer, hepatocellular carcinoma, squamous cell cancer, and osteosarcoma." (PMID 39557851, 2024). "Therefore, GNG12 may inhibit M2 polarization of TAMs, which negatively regulates MMP12 expression and thus suppresses osteosarcoma metastasis." (PMID 34691083, 2021). "Mechanical shear force-induced IGF2 overexpression promoted MMP12 expression through PI3K signaling pathways in osteosarcoma cells, thus promoting osteosarcoma metastasis and invasion." (PMID 39744430, 2025). "To identify the mediator of MCP-1-promoted osteosarcoma migration, we further examined the expression of MMP-1, MMP-2, MMP-3, MMP-7, MMP-9, MMP-12, and MMP-13 mRNA under MCP-1 stimulation." (PMID 33228783, 2020). "To identify the mediator of TSP‐2‐promoted osteosarcoma migration, we examined levels of MMP‐1, MMP‐2, MMP‐3, MMP‐7, MMP‐9, MMP‐12 and MMP‐13 mRNA expression following TSP‐2 stimulation." (PMID 33021341, 2020). "Studies have revealed that MMPs including MMP-1, MMP-2, MMP-3, MMP-7, MMP-9, MMP-12, and MMP-13 are significantly related to osteosarcoma metastasis and poor prognosis." (PMID 33228783, 2020).